IL10 (interleukin 10)
Diseases named in the same sentence as IL10 in open-access papers (continued):
Sharing a sentence is not in itself a finding about the gene and the disease.
infection (continued). "IL-10 was increased in spleen after infection with virulent RH and ME49 parasites compared with cps1-1 parasites." (PMID 27721814, 2016). "With regards to immune profiles, patent infections of S. mansoni were strongly associated with young and adolescent cohorts, elevated SEA-specific IgG4, and systemic IL-6, IL-10 and IL-13." (PMID 27152725, 2016). "In that context, infection of three-day-old mice triggered the production of IL-10 at early stages of infection, indicating that suppression of pro-inflammatory response in replication stage is advantageous to E. coli for the establishment of meningitis." (PMID 26744349, 2016). "Of particular interest, IL-10 transcripts were strongly induced only in neonatal preCD8α Clec9A+ DCs after Lm actA-/- infection whereas adult preCD8α Clec9A+ DC and adult CD8α + DCs did not." (PMID 27074026, 2016). "Overall, CFT073 was less inflammatory than F11 and is arguably a stealthier pathogen, stimulating the expression of more anti-inflammatory factors like IL-10 and producing fewer overt signs of illness during the initial stages of infection." (PMID 27303721, 2016). "In contrast, alternatively activated macrophages (M2) develop during the late stage of infection when a type II cytokine environment (IL-4, IL-10, TGF-β, etc.)predominates." (PMID 27242788, 2016). "At 1 wk post infection, mRNA levels of Il6 in the spleen were increased in Il27ra−/− mice, similar to the serum; however, Il10 and Tnf mRNA levels were similar between WT and Il27ra−/− mice." (PMID 27259855, 2016). "IL-10 producing TH1 cells have been shown to be protective in parasitic infections by limiting infection-related pathology." (PMID 27926930, 2016). "To further confirm the role of IL-10 in DENV-ADE infection, we generated four mutant K562 strains carrying homozygous deletions of IL-10 using the CRISPR-Cas9 approach." (PMID 26923481, 2016). "Our results support the notion that in the initial moments of the infection, the IL-6 concentration increased as a response to increase in parasite load and is subsequently controlled by IL-10 secretion as has been discussed for other authors." (PMID 26943639, 2016). "Originally named “cytokine synthesis inhibitory factor,” IL-10 impedes the production of a number of pro-inflammatory cytokines and chemokines secreted by antiviral T cells for the control of infection, including IFN-γ, TNF-α, and MIP-1α." (PMID 26991092, 2016). "In the present study, we found that experimental infection with L. infantum led to significantly increased IL-10 and TGF-β expression in the liver and spleen, respectively." (PMID 27171409, 2016). "When compared with H7N9-CK or H7N9-HU, H5N1 induced significantly higher levels of IL-8 at 12 h post-infection; IL-8, IL-6, IL-10 and MCP-1 at 24 h post-infection; and IL-8, IL-6, IL-10, MCP-1 and TNF-α at 48 h post-infection." (PMID 26975414, 2016). "The source of IL-10 can therefore differ depending on the infection, tissue environment and type of inflammatory insult." (PMID 27560829, 2016). "At 4 h post-infection, the transcription levels of IL-10, IL-6 and TNFα were reduced in the legS2 infected monolayers as compared to the JR32 infected monolayers." (PMID 26741365, 2016). "IL-10 is used as a weapon by the bacilli to interfere with proper macrophage activation during active infections." (PMID 27905994, 2016). "IL-10 levels were highest at 30 days post infection in untreated mice which is a known mechanism by which MTB evades immune system to establish long term infection." (PMID 27148868, 2016). "Our results strongly suggest that TNF-α/IL-10 plasma cytokine level, given its established role, is a mechanistically feasible biomarker that warrants further studies in burn trauma and infections." (PMID 27761434, 2016). "Several pathogens have evolved mechanisms that selectively up-regulate IL-10 during the course of an infection, presumably to create a more favorable microenvironment for the microbes." (PMID 27584662, 2016).
infection (continued). "Intraperitoneal infection of IL-10 -/- mice or Ab-mediated IL-10R blockade decreased ovarian VV titers slightly at 7 d.p.i.." (PMID 26991092, 2016). "On the other hand, in a P. yoelii model of infection, pDCs numbers increased by day 6 and remained high until at least day 14, and they were able to induce IL-10-expressing CD4+ T cells." (PMID 27110574, 2016). "In particular, TNF-α production contributes to the initiation of protective immunity during the early post-infection period, whereas the increase in IL-10 production that occurs in response to M. tuberculosis infection suppresses the protective Th1 response." (PMID 27148227, 2016). "Of note, we have previously shown that cell-sorted IFN-γ–YFP+ and IL-10–GFP+ T cells actively translate the respective cytokines on day 7 of infection." (PMID 27630165, 2016). "The levels of anti-inflammatory cytokine IL-10 were also significantly increased after infection and were amplified by IL-15 SA treatment." (PMID 26859674, 2016). "The frequencies of IL-10–GFP+ cells increased to variable levels in all examined tissues by day 7 of infection." (PMID 26459508, 2016). "We found that the ability of NK cells to exacerbate infection was independent from their production of IFNγ and instead due to subsequent production of the anti-inflammatory cytokine IL-10." (PMID 27295349, 2016). "Previous results showed a significant increase of tnfa, il1b, and il10 over time in zebrafish larvae infected by E. ictaluri up to 3 days post-infection." (PMID 27790411, 2016). "By two weeks after infection, lungs of pDC-depleted mice showed diminished levels of regulatory cytokines (TGF-β and IL-10), associated with increased levels of inflammatory cytokines such as IFN-γ, TNF-α, IL-12 and IL-6." (PMID 27992577, 2016). "M. avium 101 infected C57BLJ6 mice produced peak IL-10 after 2 weeks of infection and remained high throughout the period of infection." (PMID 27905994, 2016). "The qPCR results revealed that the well-known Mtb-activated genes Tnf, Csf3, Nos2 and Il10 were upregulated at 6 h and 24 h post-infection, and the fold changes at 24 h were higher than at 6 h." (PMID 26912204, 2016). "IL-10 is a key cytokine in decreasing inflammatory pathology, such as that resulting from infection by negatively regulating inflammation." (PMID 27729907, 2016). "These events establish a positive feedback loop whereby T cell-derived IL-10 further inhibits antimicrobial immune responses, allowing inevitably fatal infections to develop." (PMID 26903968, 2016). "We now show that CD11c+ cDC and monocytes are a source of IL-10 in vivo following infection of cattle with FMDV O1 Manisa and A24 Cruzeiro." (PMID 27008425, 2016). "The average TNF-α/IL-10 cytokine ratio was 0.134 ± 0.136, and average time to first recorded infection was 5.4 ± 3.0 days post-burn." (PMID 27761434, 2016). "It is further conceivable that direct infection drives the IFN-I that then is restricted to function through an autocrine fashion to increase IL-10." (PMID 26808628, 2016). "A significant reduction in CX3CR1+ IL10-producing macrophages, the in vivo analog of the Mreg species, at three weeks post infection was observed, resulting in a decrease to 50% of wild-type levels in LANCL2-/- mice." (PMID 27936058, 2016). "Here we have made an attempt to find out the answer by evaluating the infection status, level of Tregs and regulatory cytokine IL-10 in a cohort of children born to filarial infected and non infected mothers." (PMID 27861499, 2016). "While females respond to infection and trauma with increased antibody production and anti-inflammatory species such as IL-4 and IL-10, inflammation itself is usually more severe in men resulting in increased mortality in males." (PMID 27220776, 2016). "Differential expression of IL-10 in different tissues of a number of fish species upon infection with microorganisms or stimulation with LPS indicates its role in immunomodulation in fishes as well." (PMID 27689097, 2016).
infection (continued). "At 1 day post FMDV A24 Cruzeiro infection, a statistically significant increase in the expression of IL-10 by CD11c+ DC and CD14+ monocytes was observed." (PMID 27008425, 2016). "All GFP-expressing CD4+ T cells in the spleen and liver during secondary infection coexpressed YFP, showing that IFN-γ+CD4+ T cells were also the dominant source of IL-10 during secondary infection." (PMID 27630165, 2016). "The increase of IL-10 in l-rBMSCs suggests that MSCs can modulate the host immune response to infection." (PMID 27478310, 2016). "Decreased IL-10 activity in the acute phase of infection has been suggested to be beneficial to the host as it triggers enhanced immunity and clearance of the pathogen." (PMID 25430775, 2015). "The disruption of tissue architecture during SIV-infection is associated with increased expression of immunosuppressive cytokines such as TGF-β and IL-10 associated with collagen deposit and fibrosis." (PMID 26640894, 2015). "The anti-inflammatory cytokine IL-10 acts by diminishing the detrimental effects of an excessive cellular immune response elicited during the acute phase of the infection." (PMID 26575028, 2015). "Upregulation of IL-10 expression induced by mycobacteria has been proposed to inhibit host innate immune responses during infection resulting in enhanced pathogen survival." (PMID 25699042, 2015). "The application of IL-10 treatment from day 17 of infection in this study is based on pathological and pharmacological evidence that T. brucei GVR35 establishes within the brain parenchyma between 14 and 21 days post-infection." (PMID 26505761, 2015). "B. burgdorferi is a potent B cell mitogen, and infection triggers a robust antibody response, which is enhanced in Il10-/- mice." (PMID 26252010, 2015). "On the other hand, the anti-inflammatory cytokine IL-10 appears to be detrimental in the early infection." (PMID 26147698, 2015). "Kinetics of production of individual cytokines varied: TNF-α was secreted early after infection while other cytokines (IL-10, IL-13, IFN-γ) became detectable 24 to 48 hours post-infection." (PMID 26024228, 2015). "Macrophages, eosinophils and lymphocytes gathered at the site of inflammation and Th2-type cytokine secretion such as IL-4, IL-5, IL-10, and IL-13 were increased under the stimulation of worm antigen in the late infection phase." (PMID 26070790, 2015). "While we cannot prove causation nor provide evidence on which occurs first, we nevertheless provide an important link between the pathogenesis of infection/disease and IL-10 production by Th1 and aTreg cells." (PMID 26417443, 2015). "The authors showed that the combined vaccine induced a protective immunity, which was based on a Th1 response with high levels of IFN-γ prior and after challenge, as well as by low levels of IL-10 produced after infection." (PMID 26367128, 2015). "It was shown previously that miR-155 levels were elevated in infected joints of Il10-/- mice at 2 and 4 weeks post-infection." (PMID 26252010, 2015). "Then, after eight weeks p.i. the data on IL-10 levels differed greatly from those obtained at early stages of infection." (PMID 26191954, 2015). "We note that IL-12 and IFNγ (a Th1 cytokine response), and IL-10, IL-4, IL-13 or IL-5 (Th2 cytokine response) were either down-regulated during the latter phase of infection or remained unchanged." (PMID 25719526, 2015). "Th2 cytokines such as IL-5 and IL-10 were found to be increased during the early stages of infection (days 3–4 pi), while Th1 cytokines such as IL-6, IFNγ, and IL-18 did not increase until later in disease (days 6–9 pi)." (PMID 26512687, 2015). "The release of IL-6 and IL-10 in the spleens of animals dying during the acute phase of infection was similar in all three groups (P > 0.05)." (PMID 25563481, 2015).
infection (continued). "Single infection with S. mansoni cercariae leads to transient IL-10 production in the skin, which returns to naïve levels after 14 days, whilst repeated infection leads to sustained production of IL-10 between days 1–8 after exposure." (PMID 25974019, 2015). "We also predicted that Th1-mediated responses (IFN-γ) can lead to high expression of IL-10 and that infection burden regulates Th2 suppression by the Th1 response." (PMID 26619346, 2015). "The importance of IL-10 induction on T cells by IL-27 has already been shown in many disease models, such as infection with T. gondii, L. major, or Salmonella and EAE." (PMID 25633106, 2015). "High levels of IL-10 were detected in the infection control group compared with the infection control group at week 18 postinfection (P < 0.05)." (PMID 26352932, 2015). "In this work, cytokine determination showed that anti-CD25-treated mice produced lower amounts of IL-10 in the lungs when compared to control animals after 2 weeks of infection." (PMID 26512987, 2015). "Here, we show that repeated exposures of the skin to infective S. mansoni cercariae results in an early increase in IL-10 production by CD4+ T cells at the skin site of infection." (PMID 25974019, 2015). "In our model, early IL-10 production by dermal CD4+ T cells was important in limiting the extent of inflammation at the site of infection by reducing skin thickening and neutrophil recruitment." (PMID 25974019, 2015). "It is of interest however that IL-10 disappears from the EP infected chambers by 72 h after infection; perhaps it is induced again at even later times after infection." (PMID 26171605, 2015). "CD46 serves as receptor for several pathogens and dogma states that pathogens binding CD46 abuse the receptor’s ability to promote IL-10 switching, thus furthering an infection-promoting environment." (PMID 26084023, 2015). "The cytokines IL-4, IL-5 and IL-10 are thought to balance the pro-inflammatory milieu generated in an infection to keep the host tissue safe from its own inflammatory immune responses." (PMID 26566996, 2015). "Several studies have shown that helminthes can induce higher threshold ERK1/2 signaling through TLR intervention which increases IL-10 that plays a critical role in persistence of the infection." (PMID 26635448, 2015). "The induction of a Th1-like response against the LiPABP family by genetic vaccination was able to down-regulate the IL-10 predominant responses elicited by parasite LiPABPs after infection in this murine model." (PMID 25955652, 2015). "It is known that type I IFNs induce the immunosuppressive cytokine IL-10 and therefore reduced immune responses due to type I IFN-induced IL-10 contribute to loss of Mtb control in infection (McNab and others 2014)." (PMID 25714109, 2015). "Macrophage activation up-regulated TNF-α and IL-6 and down-regulated IL-10 production upon PAO1-L infection and differences between the effects of IFN-γ and GM-CSF were observed." (PMID 25706389, 2015). "The Th2-dominance in many infections such as TB is maintained by IL-10- and TGF-β mediated suppression of competing Th1 and Th17-cell populations." (PMID 26248316, 2015). "In mice killed 20 h after infection, IL-10 levels in the cerebellum also tended to be higher in mice with high vitamin D3 supply, the difference failing to reach statistical significance (P > 0.05)." (PMID 25563481, 2015). "Infected mice showed significantly increased IL-10 mRNA levels after 2 and 10 weeks of infection compared with Treg cells from uninfected mice." (PMID 26512987, 2015). "Though Treg cells are important for suppressing overall T cell response during infection and cancer, they also inhibit protective effector T cell activity by producing anti-inflammatory cytokines IL-10 and TGF-β." (PMID 25807464, 2015). "The present study showed that the polyproteins vaccine plus saponin induced a low production of IL-4 and IL-10 before infection, which was maintained in low levels after challenge." (PMID 26367128, 2015).
infection (continued). "Levels of IFN-γ were significantly reduced only at the 72 h time point and MIP-1β, RANTES, and IL-10 levels were reduced only at the 96 h post infection time point." (PMID 25984714, 2015). "In contrast, baseline levels of IL-10 were higher in young compared with aged mice, whereas young mice exhibited increased IL-10 levels following infection with S. pneumoniae." (PMID 25595646, 2015). "High concentrations of Th2 cytokines, IL-4 and IL-10 were observed in infection control group (P < 0.001) in comparison to naïve mice and a profound decline in IL-10 and IL-4 levels was witnessed in ALE and ASE treated groups (P < 0.01)." (PMID 25884649, 2015). "When compared to B-1CDP from wild type mice, the cells from IL-10 KO mice were more resistant to infection." (PMID 25933287, 2015). "Intriguingly, METH at early time points decreased IL-10 in circulation with infection than METH untreated infected mice, but quickly normalized as infection progressed." (PMID 26322025, 2015). "After infection, IL10 levels were significantly elevated at the earliest times of infection in pediatric patients who died." (PMID 25592846, 2015). "In conclusion, A. butzleri induces not only intestinal but also extra-intestinal and systemic immune responses in gnotobiotic IL-10-/- mice following peroral infection." (PMID 26406497, 2015). "Herein, we show that Treg cells residing in pulmonary lesions display a natural Treg (nTreg) phenotype, become activated in the site of infection and secrete the suppressive cytokine IL-10." (PMID 26512987, 2015). "A previous study provided the ability of a highly virulent CSFV strain to induce detectable levels of IL-10 in the serum of pigs developing the acute form at 7 days post-infection." (PMID 25938664, 2015). "Infection of IL-10 KO animals results in increased Th1 polarization, however, the proportion of the CXCR5hiPD-1hi GC Tfh subset within the IFN-γ+ population also increased significantly in these animals." (PMID 26646149, 2015). "Active infection favours induction of a Th2 skewed immune response characterised by markedly elevated levels of IL-4 and IL-10." (PMID 26377900, 2015). "On the contrary, the levels of IL-10 were significantly higher in mice immunized with either iFt or PBS versus mAb-iFt within the first 24 of infection, indicating the early anti-inflammatory properties of F. tularensis LVS." (PMID 26114641, 2015). "In this work we show that F. hepatica glycoconjugates are involved in the induction of high levels of IL-10 and IL-4 as well as in the reduction of IFNγ production by splenocytes during infection." (PMID 26720149, 2015). "IL-10, a cytokine with anti-inflammatory properties, has an important role in infection by inhibiting the immune response to pathogens." (PMID 25376937, 2015). "After 2 weeks of infection, an increase in the levels of IL-12 and IL-17 and a reduction in the levels of IL-10 were observed in Treg-depleted mice, as compared to control mice." (PMID 26512987, 2015). "The control group of patients with infections other than IE showed an elevated proportion of high producers of IL-6 and IL-8 and a moderate prevalence of high producers of IL-10." (PMID 26225421, 2015). "This dataset provides evidence that H. pylori infected macrophages up-regulate Il10 mRNA through similar means early during infection (C4)." (PMID 26367386, 2015). "Studies have shown the potent anti-inflammatory effects of IL-10 by demonstrating several functions including the ability to limit tissue damage during infections and the ability to regulate the duration and intensity of immune inflammatory reactions." (PMID 25849562, 2015). "Our study shows that while Col cl1.7 induces higher monocyte activation and, at the same time, production of IL-10, infection with Y strain leads to a lower monocyte activation but higher inflammatory profile." (PMID 26147698, 2015).